ISG15 (ISG15 ubiquitin like modifier)
Diseases named in the same sentence as ISG15 in open-access papers (continued):
Sharing a sentence is not in itself a finding about the gene and the disease.
cancer (continued). "On the other hand, very little information is available on the expression levels of free ISG15 protein vs. its conjugates in human cancers." (PMID 35159348, 2022). "Higher mRNA expression levels of both ISG15 and MT2A, found in this study as downregulated in blood samples from children with ASD, were reported to be associated with worse cancer prognosis." (PMID 36077244, 2022). "ISG15 induces cancer cell death through inhibition of NF-κB signaling and is positively correlated with IκBα or phosphorylated IκBα in ovarian high-grade serous carcinoma." (PMID 34573559, 2021). "The results showed a trend of a higher expression level in cancer tissues for ISG15, CAPN7, SEMA3A, and DYRK4 genes." (PMID 35008303, 2021). "UBE2L6 has been confirmed by conjugated ISG15, and ISG15 has also been identified as a potential cancer serological marker." (PMID 34773365, 2021). "ISG15 expression is upregulated in various cancers, including breast, hepatocellular, lung, prostate and bladder cancers." (PMID 33073304, 2021). "We and others have shown that the sensitivity of lung and other cancers to topotecan and its parent compound CPT is associated with expression of Interferon-stimulated gene 15 (ISG15)." (PMID 33860729, 2021). "Additional proteomic analyses and cancer-focused studies hint at wider-reaching, uncharacterised functions for ISG15 in genome stability." (PMID 33203188, 2020). "Such inhibition in ERK signaling by interferon treatment was abrogated in ISG15 silenced cancer cells, suggesting ISG mediated interferon-induced inhibition of ERK signaling." (PMID 30469497, 2018). "Growing studies show that ISG15 expression and protein ISGylation are dysregulated in numerous types of cancer and play a crucial role in tumorigenesis." (PMID 29350614, 2018). "Various numbers of immune cells such as lymphocytes, neutrophils, and monocytes present in the stromal, which have been shown to express ISG15, will skew the ISG15 expression levels in the cancer cells and make the survival correlation insignificance." (PMID 30469497, 2018). "Skp2, as a part of the SCF-Skp2 E3 ubiquitination complex, is required for the removal of several key proteins as Myc, FOXO1, cancer-derived Smad 4 mutants, ISG15 isopeptidase UBP43, and other proteins." (PMID 26682002, 2016). "In cancer cells, ISG15 exists in two forms: free (intracellular) and conjugated to cellular proteins (ISGylation)." (PMID 26919245, 2016). "In this review, we discuss the findings of recent studies with regard to the role of ISG15 pathways in cancers of the digestive system." (PMID 27626310, 2016). "Excluding the seven shedding chips, 197 of 202 (97.5%) cases showed primary cytoplasmic staining of ISG15 in cancer cells, with occasional immunoreactivity observed in the stromal lymphocytes." (PMID 26919245, 2016). "In this review, we describe the biological functions of ISG15, and discuss evidence from recent studies that highlight the potential roles of ISG15 in tumorigenesis and response to treatment in cancers of the digestive system." (PMID 27626310, 2016). "More importantly, enforced ISG15 leads to cancer cell apoptosis and decreased cancer cell proliferation." (PMID 27659523, 2016). "In the last decade, ISG15 has been frequently reported in various cancer tissues including hepatocellular carcinoma, pancreatic cancers, colorectal cancer." (PMID 27659523, 2016). "Taken together with previous findings that ISG15 promotes oncogenesis, it should be cautious when making a conclusion of ISG15 and ISGylation into cancer therapy." (PMID 27659523, 2016). "Future studies are needed to investigate the role of ISG15-dependent Wnt/beta-catenin signaling suppression in cancers of the digestive system." (PMID 27626310, 2016).
cancer (continued). "To evaluate the anti-cancer activity of ISG15 in vivo, we next established a human cancer xenograft model in nude mice using HeLa cells which were infected with lentiviral ISG15 or empty virus." (PMID 27659523, 2016). "ISG15 overexpression promoted a cancer stem cell phenotype in NPC cells, including increased colony and tumorsphere formation abilities, pluripotency-associated genes expression, and in vivo tumorigenicity." (PMID 26919245, 2016). "Intracellular ISG15 exhibits protumor capacities such as promotion of the proliferation and migration of cancer cells." (PMID 26919245, 2016). "This study along with these previous studies thus suggest that in contrast to promoting tumorigenesis, ISG15 also displays anti-cancer activities." (PMID 27659523, 2016). "Although the role of ISG15 in host defenses against bacterial and viral pathogens is well documented, very little is known about its role in cancer." (PMID 25749047, 2015). "In cancer cells, ISG15 is detected as free (intracellular) and conjugated to cellular proteins (ISGylation)." (PMID 25749047, 2015). "Interferon-Stimulated Gene 15 (ISG15), an antagonist of the canonical ubiquitin pathway, is frequently overexpressed in various cancers." (PMID 25749047, 2015). "In contrast to normal cells, Isg15 is highly expressed in numerous primary human cancers, and its expression is known to be required for oncogene-mediated transformation." (PMID 25071020, 2014). "To understand the potential role of Isg15 in the regulation of tumorigenesis in vivo, we carried out the bioinformatics analysis of different types of human cancers in order to identify subsets with high level of active Src." (PMID 25071020, 2014). "We used the HepG2 cell line as a model system to study the effects of ISG15 expression on cancer cell apoptosis." (PMID 24024201, 2013). "In line with this paradoxical phenotype, ISG15 is elevated both in stromal and cancer cells." (PMID 40904511, 2025). "Therefore, we investigated the co-expression relationship with 24 immune checkpoints in pan-cancer, revealing that ISG15 expression generally exhibits positive correlations with a host of checkpoints and negative correlations with PVRL3." (PMID 40208307, 2025). "Extracellular ISG15 has been shown to have activity in cancer as well." (PMID 40719862, 2025). "We comprehensively assessed the prognostic significance of ISG15 across pan-cancer." (PMID 40208307, 2025). "Specifically, ISG15 expression was upregulated in viral infections including Coronarvirus Disease-2019 (COVID-19), autoimmune diseases and in some types of cancer." (PMID 40936712, 2025). "Further investigation into the role of extracellular ISG15 may uncover novel therapeutic strategies for infectious diseases, cancer, and inflammatory conditions." (PMID 40719862, 2025).
cancer (continued). "Such mechanistic insights may facilitate the development of therapeutic strategies targeting dysregulated ISG15 pathways in diseases, such as cancer, neurodegenerative disorders, and inflammation." (PMID 40774387, 2025). "ISG15 plays an oncogenic role in multiple cancers by regulating diverse mechanisms." (PMID 40208307, 2025). "All these findings suggest that ISG15 participates in the biological progression of cancer." (PMID 40208307, 2025). "Additionally, free-ISG15 promotes cancer stem cell-like features in pancreatic ductal adenocarcinoma (PDAC), with this effect being regulated by TRIM29 and CAPN3." (PMID 38400136, 2024). "Moreover, autophagy and regulation of the cancer microenvironment are some of the molecular processes in which ISG-15 is involved." (PMID 38790257, 2024). "Moreover, ISG15 emerges as a promising adjuvant in vaccine development, enhancing immune responses against viral antigens and demonstrating efficacy in cancer models." (PMID 38400136, 2024). "The study suggests that focusing on understanding of the regulatory effect of ISG15 conjugation to SIRT1 could enhance cancer treatments." (PMID 38443596, 2024). "In PC, ISG15 is critical for cancer stem cell (CSC) maintenance 24-26." (PMID 38385083, 2024). "To address this issue, we hypothesized that ISG15 exerts a stimulatory influence on cancer-related traits like cell proliferation, invasion, and metastasis in ccRCC." (PMID 38951255, 2024). "However, very little information is available on the expression levels of the free ISG15 protein and its conjugates in human cancers." (PMID 38939897, 2024). "As a result, elucidating the mechanisms by which ISG15 and its conjugation mediate sensitivity or resistance to cancer therapies could be a goal in improving cancer patient survival." (PMID 36771004, 2023). "Notably, ISG15 displays different levels in different cancers and plays a key role in the occurrence and development of tumors." (PMID 36771004, 2023). "ISG15 has been demonstrated to inhibit cancer progression and is often dysregulated within cancers." (PMID 36911698, 2023). "The high levels of ISG15 in several cancer types suggest the potential of ISG15 as a biomarker." (PMID 37711589, 2023). "Our study shows that ISG15, as a post-translational modifier of PD-L1, reduces the stability of PD-L1 and may be a potential therapeutic target for cancer immunotherapy." (PMID 37217923, 2023). "The dual activities of ISG15 in cancer may be related to the crosstalk of ISG15 with other molecular pathways." (PMID 37711589, 2023). "Extracellular-free ISG15 has been reported to play an important role in various cancers." (PMID 36771004, 2023). "In consideration of ATC featured with high cancer stem cell-like characteristics, we tried hard to determine whether high expression of ISG15 was inseparable from cancer stem cells." (PMID 37501099, 2023). "Nevertheless, more studies are required to understand the role of ISG15 in cancer therapies." (PMID 37711589, 2023). "Next, we examined whether ISG15 was the critical factor in maintaining cancer stem cell-like characteristics of ATC." (PMID 37501099, 2023). "In the context of cancer, free ISG15 may also be secreted and may act as a potential factor in the microenvironment of malignant tumors." (PMID 37711589, 2023). "Moreover, it is important to address the possible role of ISG15 pathway in the premature aging side effects triggered by anti-cancer therapies due to activation of DNA damage responses in healthy tissues." (PMID 37025175, 2023). "Novel findings about the molecular mechanisms of ISG15 in tumorigenesis may be useful in preventing, treating, and controlling cancer." (PMID 37711589, 2023). "ISG15 expression is also deregulated in other cancer types developed in the central nervous system." (PMID 37711589, 2023).
cancer (continued). "Notably, the expression of the ISGylation enzymes and the USP18 deISGylase are critical in determining the relationship between ISGylation and free ISG15 levels and, consequently, their functions in cancer." (PMID 37711589, 2023). "However, ISG15 and ISGylation in tumorigenesis are controversial, likely due to the genetic background of cancers, type of tissues, stage of cancer, and concomitant alterations in particular cancer-related signal transduction pathways." (PMID 36319753, 2022). "All available data suggest that intracellular ISG15 conjugates and free ISG15 could harm patients by stabilizing cellular proteins that promote cancer, and secreted free ISG15 may benefit patients by modulating immune system functions." (PMID 35159348, 2022). "Upregulation of BATF2 and downregulation of ISG15 and MT2A were reported to reduce cancer risk." (PMID 36077244, 2022). "Notably, dysregulation of ISG15 in cancer cells promotes the accumulation of cytosolic DNA, activation of cGAS-STING and chronic induction of type I IFN signaling in a potential auto-inductive loop." (PMID 35681561, 2022). "Furthermore, increased ISG15 conjugation confers anti-cancer drug (e.g., Topotecan) sensitivity to tumors, validating the potential of ISG15 conjugates to serve as a biomarker for drug sensitivity in cancer patients." (PMID 35159348, 2022). "Therefore, undoubtedly, many research groups should be encouraged to study why cancer cells upregulate ISG15 and how its upregulation gives an advantage to cancer cell growth." (PMID 36319753, 2022). "We also highlight new insights into the roles of ISG15 and ISGylation not only in physiology but also in the pathogenesis of various human diseases, especially in cancer, which could contribute to therapeutic intervention in human diseases." (PMID 36319753, 2022). "Therefore, future studies focusing on ISG15 in other cancer cells exposed to μg should be performed." (PMID 35328492, 2022). "It is possible that accumulated free ISG15 stabilizes USP18 in cancer cells expressing low levels of UBE1L and high levels USP18, which in turn removes the ISG15 degradation signal from the target proteins (e.g., Cyclin D1), consequently stabilizing these protumor proteins." (PMID 35159348, 2022). "Furthermore, the role of free ISG15 conflicts with the role of its conjugation in terms of cancer pathogenesis, suggesting the necessity of further investigation." (PMID 36319753, 2022). "Proteins proposed for spheroid formation are ASAP1 and stabilize ISG15 in cancer cells." (PMID 35328492, 2022). "ISG15 and its conjugation affect the progression and treatment response in different cancers." (PMID 36189312, 2022). "However, ISG15 has been shown to induce proliferation, apoptotic resistance, invasion and migration in cancer cells." (PMID 33718235, 2021). "ISG15 alters multiple proteins, including focal adhesion protein, action binding or modifying proteins to improve their function or increase their stability to facilitate the cancer cell migration, such as binding with Rac1 in oral squamous cell carcinoma." (PMID 33073304, 2021). "Recently, it has been reported that ISG15 plays a strikingly ambiguous role in cancers." (PMID 33797839, 2021). "Thereby, the difference between free and conjugated form of ISG15 might be an alternative explanation for its paradoxical function in distinct cancers." (PMID 33797839, 2021). "Further understanding of the molecular trajectory of the ubiquitin-like protein ISG15 may lead to new therapeutic strategies for antiviral treatment, immune function regulation, and cancer treatment." (PMID 34901029, 2021). "However, ISG15 knock‐down significantly increased cancer stem cell‐like features of SKOV3 and A2780 cells, including colony formation, migration, invasion and spheroid formation." (PMID 33797839, 2021). "High immunoexpressions of ISG15 were observed in both normal and carcinoma tissues." (PMID 34439992, 2021).
cancer (continued). "The expression of ISG15, and several other factors that regulate ISGylation, frequently exhibit dysregulation in different cancer types, but the mechanisms responsible for these effects and their outcomes are not clear, and may depend upon the cancer type." (PMID 31318078, 2020). "Additionally, elevated ISG15 sensitised cancer cells to both CPT and the PARP inhibitor olaparib, raising intriguing possibilities regarding the treatment and stratification of cancer patients." (PMID 33203188, 2020). "Furthermore, Sainz and colleagues observed macrophages increase the expression and secretion of ISG15 when cocultured with cancer stem cells." (PMID 33424843, 2020). "Moreover, ISG15 expression is often perturbed in cancer cell lines and can impact on drug resistance." (PMID 33203188, 2020). "ISG15 has been shown to enhance the tumorigenic potential of cancer stem cells." (PMID 30987352, 2019). "ISG15 has also been reported to inhibit cancer cell growth and promote apoptosis." (PMID 30952992, 2019). "Given the increasing importance of both DTX3L and ISG15 in tumorigenic regulation, the DTX3L-ISG15 regulatory axis may play a pivotal role in cancer development and progression, and deserves further study in TNBC." (PMID 29350614, 2018). "Furthermore, a decreased level of total ERK1 protein expression was observed in ISG15 transfected cancer cells." (PMID 30469497, 2018). "ISG15 is found to be elevated in many human carcinomas and cancer cell lines." (PMID 29296177, 2017). "Although the detailed mechanisms are lacking, ISG15 modulates pluripotency-associated genes expression, maintains cancer stem cell phenotype, and promotes tumorigenesis." (PMID 27659523, 2016). "Therefore, the present study demonstrated that ISG15 induces cancer cell apoptosis by disrupting the NF-κB signaling pathway." (PMID 27659523, 2016). "However, it has also been reported that free ISG15 suppressed the growth of cancer cells via its immunomodulatory properties in vivo." (PMID 26919245, 2016). "Notably, these results were consistent with previous studies, in which ISG15 was significantly induced by classic anti-cancer camptothecin and all-trans retinoic acid." (PMID 27659523, 2016). "Therefore, ISG15 probably displays itself as a double-edged sword in cancer dependent on its free form or conjugation context." (PMID 27659523, 2016). "Recent studies have reported that ISG15 is frequently overexpressed in various cancers." (PMID 26919245, 2016). "Because ISG15 was upregulated by anti-cancer agents, we wondered whether it could suppress cancer cell proliferation." (PMID 27659523, 2016). "ISG15 was also induced by classic anti-cancer agent camptothecin." (PMID 27659523, 2016). "Therefore, we describe the functions of ISG15 in IFN-mediated immune responses that are relevant to innate immunity to cancer." (PMID 27626310, 2016). "Actually several key proteins have been found involved in ISG15-induced cancer cell apoptosis." (PMID 27659523, 2016). "As a key player in cancer-association inflammation, there is no doubt that ISG15 is involved in carcinogenesis which has been demonstrated in several lines of investigative evidence." (PMID 27659523, 2016). "These reported findings partly explain the anti-cancer activity of ISG15." (PMID 27659523, 2016). "However, several other studies show that ISG15 also displays anti-cancer activities, for example, it affects the cancer microenviroment and inhibits cancer progression." (PMID 27659523, 2016). "Similar to our cancer-related study, several other literature studies have indicated that free ISG15 may also function to help the immune system to recognize pathogen (viruses and bacteria) infected cells for their destruction in the human body." (PMID 25749047, 2015). "The exact role of Isg15 in oncogene-mediated transformation or in cancer however is still unclear." (PMID 25071020, 2014).